GPRC5A (G protein-coupled receptor class C group 5 member A)
Diseases named in the same sentence as GPRC5A in open-access papers (continued):
Sharing a sentence is not in itself a finding about the gene and the disease.
colorectal cancer (12 papers, 2014 to 2025). A primary or metastatic malignant neoplasm that affects the colon or rectum. "Strong cytoplasmic expression of GPRC5A in colorectal cancer tissues is significantly associated with disease recurrence in Dukes' A-C (stage 1-3) patients when compared to low or negative expression of GPRC5A in cancer tissues." (PMID 25621293, 2014). "In this work, we study the effects of vitamin D (VD, cholecalciferol) and retinoic acid (RA) on GPRC5A mRNA expression in the colorectal cancer cell lines Caco-2 and T84." (PMID 40427604, 2025). "Previous studies have only associated GPRC5A with the early stages of lung carcinogenesis; however, our experiments indicate that GPRC5A is significantly overexpressed in both breast and colorectal cancers." (PMID 40608007, 2025). "In colorectal cancer, GPRC5A promotes tumor formation by regulating NF-κB-mediated Vanin-1 expression and oxidative stress." (PMID 38634049, 2024). "Knockdown of GPRC5A with siRNA can promote tumor cell apoptosis and reduce cell proliferation in colorectal cancer." (PMID 33788883, 2021). "Using bioinformatics, we found that high levels of GPRC5A mRNA correlate with hypoxia gene signatures and poor survival outcomes in colorectal cancer patients." (PMID 30143543, 2018). "Taken together, our in vitro and in vivo findings show that hypoxia and HIFs regulate GPRC5A and that high GPRC5A expression is an indicator of poor prognosis in colorectal cancer patients." (PMID 30143543, 2018). "GPRC5A is highly expressed in colorectal cancer (CRC), and elevated GPRC5A expression is significantly associated with inferior prognosis." (PMID 30417009, 2018). "In colorectal cancer, GPRC5A is abundantly present in tumor epithelium with the neuroendocrine cells showing strong staining on the plasma membrane." (PMID 25621293, 2014). "In SW480 colorectal cancer cells, glycosylated GPRC5A interacts with Gal-3." (PMID 41090797, 2025). "Similarly, several studies suggest that overexpression of GPRC5A predicts poor prognosis in gastric, pancreatic, and colorectal cancer patients." (PMID 33788883, 2021). "In colorectal cancer study, GPRC5A was induced by hypoxia and was regulated major by HIFs." (PMID 33753999, 2021). "Furthermore, we find that GPRC5A is upregulated in the colonic epithelium of patients with mesenteric ischaemia, and in colorectal cancers high GPRC5A correlates with hypoxia gene signatures and poor clinical outcomes." (PMID 30143543, 2018). "Furthermore, we found that high GPRC5A transcripts closely correlated with poor survival outcomes in colorectal cancer patients." (PMID 30143543, 2018). "Finally, bioinformatic analysis on a transcriptomics dataset (GSE24551) from 320 primary colorectal cancers revealed that GPRC5A mRNA levels strongly correlated with HIF and hypoxia gene signatures." (PMID 30143543, 2018). "GPRC5A and colorectal cancer: In normal colon tissue, GPRC5A is expressed at low levels." (PMID 25621293, 2014). "In these samples, GPRC5A level is higher in both metastatic and non-metastatic colorectal cancer than it is in polyps indicating that GPRC5A could be used as a biomarker in the diagnosis of colorectal cancer." (PMID 25621293, 2014).
prostate carcinoma (12 papers, 2020 to 2025). A carcinoma that arises from epithelial cells of the prostate gland. "High expression of GPRC5A is associated with increased bone-metastatic lesions and lower survival rates in patients with prostate cancer." (PMID 38260135, 2023). "The expression of GPRC5A correlates with bone metastasis and the Gleason score in prostate cancer patients, suggesting its potential as a therapeutic target and prognostic marker for advanced prostate cancer." (PMID 40860192, 2025). "Using this method, we identified GPRC5A as a molecule involved in the bone metastasis of prostate cancer and found that LIM1 contributes to the malignant potential of endometrial cancer." (PMID 41263259, 2025). "A recent study reported that a GPRC5A knockout markedly reduced the proliferation and migration of progressive prostate cancer cells." (PMID 34823491, 2021). "GPRC5A was also reported to act as a potential oncogene in prostate cancer and pancreatic ductal adenocarcinoma." (PMID 32766708, 2020). "Interestingly, GPRC5A might have contrasting roles in different solid malignant tumors, such as facilitating cell proliferation in prostate cancer, whereas suppressing cell viability and inducing cell apoptosis in LC." (PMID 37564290, 2023). "A study on PC3 prostate cancer cells demonstrated that following GPRC5A knockout with CRISPR/Cas9, cell proliferation was significantly decreased via induction of cell cycle arrest at the G2/M phase in GPRC5A KO PC3 cells." (PMID 38260135, 2023).
bladder cancer (10 papers, 2015 to 2025). "GPRC5A variants may drive self-renewal of bladder cancer stem cells according to single-cell RNA-seq analysis." (PMID 34660776, 2021). "Targeted therapy for bladder cancer and bladder cancer stem cells can be achieved via the circ_Gprc5a-peptide-Gprc5a axis." (PMID 40034125, 2025). "One study revealed that circGPRC5A-peptide-GPRC5A can be utilized to target bladder cancer and bladder cancer stem cells." (PMID 38057879, 2023). "In bladder cancer, however, circGPRC5A is shown to be translated into a GPRC5A protein to regulate the bladder cancer stem cell phenotype in promoting tumorigenicity." (PMID 37950151, 2023). "Mutation of GPRC5A promote cell differentiation and self-renewal pathway and significantly increased the sphere-forming ability of bladder cancer non-stem cells." (PMID 37143105, 2023). "Gprc5a is an essential protein in bladder cancer stem cells." (PMID 34697887, 2021). "However, in the absence of a protein encoded by circ‐Gprac5a, Gprc5a did not function, which indicated that the circ‐Gprc5a‐peptide‐Gprc5a pathway was closely associated with bladder cancer progression." (PMID 34697887, 2021). "Urinary EV SLC2A1, GPRC5A and KRT17 were overexpressed in pT1 and higher stage bladder cancer by 20.6-fold, 18.2-fold and 29.5-fold, respectively." (PMID 30214686, 2018). "Yang using single-cell sequencing of specimens from three bladder cancers identified six genes not previously found in bladder cancer and revealed that co-mutations in ARID1A, GPRC5A and MLL2 enhanced the self-following ability of bladder cancer cells." (PMID 34895349, 2021). "KRT17 expression was significantly high in pT1 (11.5-fold, p = 2.7 x 10-7), pT2 and higher stages (15.0-fold, p = 4.0 x 10-4), G2 (1.4-fold, p = 0.022) and G3 bladder cancer (6.7-fold, p = 1.8 x 10-6), which was consistent with the expression of SLC2A1 and GPRC5A." (PMID 30214686, 2018). "GPRC5A expression was also significantly elevated in pTis (8.3-fold, p = 0.0084), pT1 (19.5-fold, p = 2.1 x 10-8), G2 (2.0-fold, p = 0.048) and G3 bladder cancer (11.5-fold, p = 8.1 x 10-7) therefore may be useful to supplement SLC2A1 especially for the detection of pTis bladder cancer." (PMID 30214686, 2018).
chronic obstructive pulmonary disease (8 papers, 2014 to 2024). A chronic and progressive lung disorder characterized by the loss of elasticity of the bronchial tree and the air sacs, destruction of the air sacs wall, thickening of the bronchial wall, and mucous accumulation in the bronchial tree. "Consistent with this, GPRC5A expression was found to be decreased in patients with chronic obstructive pulmonary disease (COPD) and non-small-cell lung cancer." (PMID 33187367, 2020). "GPRC5A and other diseases: In chronic obstructive pulmonary disease (COPD) patients, the levels of GPRC5A protein were significantly lower in normal bronchial epithelia (NBE) compared with healthy controls." (PMID 25621293, 2014). "Moreover, GPRC5A is repressed in most of NSCLC and all of chronic obstructive pulmonary disease (COPD)." (PMID 32060421, 2020).
colon carcinoma (8 papers, 2017 to 2025). "Studies have shown that GPRC5A is a potential biomarker for colon cancer and promotes the occurrence of tumors in colitis-associated cancers by stimulating vanin-1 expression and oxidative stress." (PMID 33505587, 2021). "GPRC5a is over expressed in pancreatic, breast, gastric and colon cancer, and it has been shown that overexpression of RAI3 predict poor prognosis in hepatocellular carcinoma." (PMID 28114355, 2017). "GPRC5A is over-expressed in colon cancer and hepatocellular carcinoma." (PMID 29283424, 2017). "We propose that highly expressed GPCRs in cancer cells (for example, GPRC5A in PDAC and colon cancer cells and GPR68 in PDAC CAFs) may contribute to the malignant phenotype, serve as biomarkers and/or may be novel therapeutic targets for the treatment of cancer." (PMID 29872392, 2018).
hepatocellular carcinoma (7 papers, 2014 to 2023). A malignant tumor that arises from hepatocytes. "Conflicting information exists concerning GPRC5A's expression status in hepatocellular carcinoma (HCC)." (PMID 30417009, 2018). "In one study, it was reported that GPRC5A expression is higher in hepatocellular carcinoma (HCC) than in para-tumor or in normal liver tissues." (PMID 25621293, 2014). "GPRC5A and hepatocellular carcinoma: Based on the currently available evidence it is not clear whether in liver GPRC5A acts an oncogene or as tumor suppressor." (PMID 25621293, 2014).
non-small cell lung carcinoma (7 papers, 2014 to 2023). A group of at least three distinct histological types of lung cancer, including non-small cell squamous cell carcinoma, adenocarcinoma, and large cell carcinoma. "By immunoblot, Q-PCR, and immunohistochemical (IHC) staining, we found that ceruloplasmin, lipocalin-2, and periostin are not only upregulated in the lung tumor tissues of Gprc5a-ko mice, but also in human non-small cell lung cancer (NSCLC)." (PMID 28088789, 2017). "In the disease context, GPRC5A was originally reported as a tumor suppressor in non-small cell lung carcinoma." (PMID 25621293, 2014). "GPRC5A and non-small cell lung carcinoma: In non-small cell lung carcinoma (NSCLC), GPRC5A mRNA levels are lower than in adjacent normal tissues." (PMID 25621293, 2014). "GPRC5A expression is frequently suppressed in majority of non-small cell lung cancers (NSCLCs), however, elevated GPRC5A is still observed in a small portion of NSCLC cell lines and tumors, suggesting that the tumor suppressive function of GPRC5A is inhibited in these tumors by an unknown mechanism." (PMID 25311788, 2014).
head and neck squamous cell carcinoma (6 papers, 2007 to 2023). A squamous cell carcinoma that arises from any of the following anatomic sites: lip and oral cavity, nasal cavity, paranasal sinuses, pharynx, larynx, and salivary glands. "However, the molecular mechanisms underlying GPRC5A deficiency in head and neck squamous cell carcinoma (HNSCC) are still unclear." (PMID 28270740, 2017). "ΔNp63α may interact with actin-like protein 6A (ACTL6A), which is a subunit of SWI/SNF CRC and co-amplified with ΔNp63α in head and neck squamous cell carcinoma (HNSCC); this collaboration leads to a downregulation of tumour suppressors such as WWC1 and GPRC5A." (PMID 36760085, 2023).
ovarian carcinoma (6 papers, 2020 to 2025). A malignant neoplasm originating from the surface ovarian epithelium. "Compared to previous studies, we analyzed the composition of NK92 cells for the first time in this study and demonstrated that NK92 cell-derived exosomes containing miR-31-5p affect ovarian cancer progression by inhibiting GPRC5A expression." (PMID 41306963, 2025). "In this study, we characterized the protein and miRNA profiles of NK92 cells and their exosomes, establishing their capacity to inhibit ovarian cancer progression through GPRC5A degradation." (PMID 41306963, 2025). "Functional assays revealed that miR-31-5p promotes apoptosis and suppresses proliferation/metastasis in ovarian cancer cells by degrading GPRC5A." (PMID 41306963, 2025). "The low expression of ANP32E, STAT1, GPRC5A, EGFL6, and PMP22 was positively associated with overall survival time of ovarian cancer." (PMID 34660776, 2021). "Combining TCGA ovarian cancer dataset, we identified differentially expressed marker genes that were significantly associated with prognosis of ovarian cancer, including ANP32E, STAT1, GPRC5A, EGFL6, PMP22, FBXO21, and CYB5R3." (PMID 34660776, 2021). "We found that the expression levels of STAT1, ANP32E, GPRC5A, and EGFL6 were all significantly higher in ovarian cancer tissues compared with normal tissues." (PMID 34660776, 2021). "This study identifies GPRC5A as a marker for poor therapy response and vulnerability of the resistant cells to RSK1/2‐EphA2‐pS897 pathway inhibition in ovarian cancer." (PMID 32115889, 2020). "Furthermore, marker genes, STAT1, ANP32E, GPRC5A, and EGFL6, were highly expressed in ovarian cancer, while PMP22, FBXO21, and CYB5R3 were lowly expressed in ovarian cancer." (PMID 34660776, 2021). "Besides, in ovarian cancer, it was shown that the adaptive ERK1/2-RSK1/2-EphA2-GPRC5A signaling switch triggered chemotherapy resistance and identified GPRC5A as a marker for abysmal ovarian cancer outcome." (PMID 33753999, 2021).
glioma (4 papers, 2021 to 2024). A benign or malignant brain and spinal cord tumor that arises from glial cells (astrocytes, oligodendrocytes, ependymal cells). "Our current findings identified that circ‐UBAP2 silencing impeded glioma malignant progression partially by downregulating GPRC5A through targeting miR‐1205 and miR‐382." (PMID 33543830, 2021). "In summary, our current work demonstrated that circ‐UBAP2 silencing impeded glioma malignant progression by downregulating GPRC5A by targeting miR‐1205 and miR‐382." (PMID 33543830, 2021). "In order to elucidate the link between GPRC5A and miR‐1205 or miR‐382 in glioma progression, we overexpressed GPRC5A in cells transfected with miR‐1205 or miR‐382 mimic." (PMID 33543830, 2021). "Taken together, these results suggested that miR‐1205 and miR‐382 regulated the function behaviors of glioma cells in vitro by targeting GPRC5A." (PMID 33543830, 2021). "GPRC5A, a G-protein-coupled receptor gene, is upregulated in many cancer types, including glioma." (PMID 39794971, 2024). "Besides circZNF800, only miR-382-5p is also reported to be sponged by another circular RNA circUBAP2 to regulate GPRC5A (G protein-coupled receptor class C group 5 member A) expression in glioma." (PMID 37950151, 2023). "Additionally, miR-1205 and miR-382 were functional targets of GPRC5A in modulating glioma cell activities." (PMID 35883576, 2022). "Similarly, the transfection of GPRC5A overexpressing plasmid reversed miR‐382 overexpression‐mediated GPRC5A downregulation in the two glioma cell lines." (PMID 33543830, 2021). "Moreover, GPRC5A was a functional target of miR‐1205 and miR‐382 in regulating glioma cell behaviors." (PMID 33543830, 2021). "Interestingly, we first highlighted that GPRC5A was an importantly functional target of miR‐1205 and miR‐382 in suppressing glioma cell progression." (PMID 33543830, 2021). "A previous study demonstrated the oncogenic role of GPRC5A in glioma." (PMID 33543830, 2021). "Moreover, cirBAP2 induced GPRC5A expression in glioma cells via miR-1205 or miR-382." (PMID 35883576, 2022). "Furthermore, circ‐UBAP2 mediated GPRC5A expression through miR‐1205 or miR‐382 in glioma cells." (PMID 33543830, 2021). "Additionally, by contrast, GPRC5A was prominently overexpressed in glioma tissues and cell lines." (PMID 33543830, 2021). "Here, we identified two novel mechanisms, the circ‐UBAP2/miR‐1205/GPRC5A and circ‐UBAP2/miR‐382/GPRC5A axes, in the development of glioma, highlighting circ‐UBAP2 inhibitor as a potential therapeutic strategy for glioma." (PMID 33543830, 2021).
melanoma (4 papers, 2018 to 2025). A malignant, usually aggressive tumor composed of atypical, neoplastic melanocytes. "For example, of the 16 total genes driving the association between melanoma and nevus count, only two (MTAP and ERVFRD‐3) were shared by all three tissues, and six (MAFF, HEBP1, HTR7P1, EMP1, GPRC5A, C9orf66) were specific to melanocyte." (PMID 38308491, 2024). "In a bivariate analysis combining the nevus results with a recent melanoma GWAS meta-analysis (12,874 cases, 23,203 controls), SNPs near GPRC5A, CYP1B1, PPARGC1B, HDAC4, FAM208B, DOCK8, and SYNE2 reached global significance, and other loci, including MIR146A and OBFC1, reached a suggestive level." (PMID 30429480, 2018). "We have highlighted eight novel loci, including the genes HDAC4, SYNE2, and most notably GPRC5A, where quite large samples of melanoma cases or nevus count were not sufficiently powerful to reach formal genome-wide significance in univariate analyses, but the combined evidence is conclusive." (PMID 30429480, 2018).
adenoma (3 papers, 2010 to 2022). A neoplasm arising from the epithelium. "The average numbers of hyperplastic lesions and adenomas increased to 61, and 14, respectively, in the lungs of Gprc5a -/- mice exposed to both NNK and NTHi." (PMID 22239913, 2012). "The lungs of Gprc5a -/- mice exposed to NTHi alone showed an average of 5 foci of bronchiolar and/or alveolar hyperplasia and 1 adenoma, with infiltration of neutrophils, macrophages and lymphocytes in the airways and alveoli." (PMID 22239913, 2012). "The incidence of tumors increased with time in the NNK-treated Gprc5a−/− mice reaching 50% and 83% for adenomas and adenocarcinomas, respectively at 18 months compared to 16.7% and 16.7%, respectively in the control mice." (PMID 20686609, 2010). "We previously found that Gprc5a−/− mice, when exposed to tobacco carcinogen, develop accelerated premalignant lesions (hyperplasias and adenomas) compared to wild-type littermates and harbor in their tumors somatic activating mutations in Kras G12D that are highly pertinent to human LUAD in smokers." (PMID 36142843, 2022). "In this study we found that exposure of young mice to NNK (only two i.p. injections separated by one week) shortened the time to tumor development and increased the incidence, multiplicity, and size of both adenomas and adenocarcinomas in Gprc5a-knockout mice compared to control mice." (PMID 20686609, 2010). "The lungs of Gprc5a -/- mice exposed to NNK alone showed an average of 13 foci of bronchiolar and/or alveolar hyperplasia, and an average of 2 adenomas." (PMID 22239913, 2012).